DKK3 (dickkopf Wnt signaling pathway inhibitor 3)
Diseases named in the same sentence as DKK3 in open-access papers (continued):
Sharing a sentence is not in itself a finding about the gene and the disease.
endometrial cancer (5 papers, 2015 to 2021). Primary or metastatic malignant neoplasm involving the endometrium (mucous membrane that lines the endometrial cavity). "For example, DKK3 is expressed at a low level in endometrial cancer, indicating that DKK3 can also be used as a new biomarker in endometrial cancer." (PMID 33013201, 2020). "Activation of the Wnt signaling pathway via alteration of the APC, Axin, CTNBB1, Wnt ligands, Wnt inhibitors Dickkopf3 (DKK3) and Dickkopf1 (DKK1), or the secreted Frizzled-related proteins may be a key driving event in the development of endometrial cancer." (PMID 34068065, 2021).
endothelial dysfunction (5 papers, 2017 to 2025). In vascular diseases, endothelial dysfunction is a systemic pathological state of the endothelium (the inner lining of blood vessels) and can be broadly defined as an imbalance between vasodilating and vasoconstricting substances produced by (or acting on) the endothelium. "The chronic inflammation and bone-destructive mechanisms seen in periodontitis may elevate systemic levels of inflammatory mediators, such as DKK-3, contributing to endothelial dysfunction, vascular inflammation, and plaque formation." (PMID 41356214, 2025). "In a study in knock-out mice for the gene DKK-3 with a subsequently failed expression of this protein, a significant endothelial dysfunction has been reported, evidenced by an inversely proportional relationship between the middle-intimate layer of the carotid artery and plasmatic levels of DKK-3." (PMID 33317034, 2020).
esophageal squamous cell carcinoma (5 papers, 2020 to 2025). Esophageal squamous cell carcinoma (ESCC) is a type of esophageal carcinoma (EC) that can affect any part of the esophagus, but is usually located in the upper or middle third. "Furthermore, it has been observed that hypermethylation of certain Wnt inhibitors, namely runt‐related transcription factor 3 (RUNX3), DKK‐3, and sFRP1, is positively associated with the recurrence of esophageal squamous cell carcinoma (ESCC)." (PMID 37901797, 2023). "About half of the tumor lesions of patients with esophageal squamous cell carcinoma (ESCC) express Dkk-3." (PMID 36497305, 2022). "However, some cancer types, including HNSCC/OSCC and esophageal squamous cell carcinoma, will express DKK3." (PMID 40917921, 2025). "However, some types of cancers, including HNSCC/OSCC and esophageal squamous cell carcinoma, specifically express DKK3, and in such cancers, DKK3 exerts oncogenic function via activation of Akt signaling." (PMID 40917921, 2025). "Our previous studies have demonstrated that DKK3 expression is observed in certain cancers, such as OSCC and esophageal squamous cell carcinoma, and DKK3 increases tumor malignancy through Akt activation in such cancers, while its expression is lost in many kinds of malignancies." (PMID 40917921, 2025).
leukemia (5 papers, 2004 to 2018). A malignant (clonal) hematologic disorder, involving hematopoietic stem cells and characterized by the presence of primitive or atypical myeloid or lymphoid cells in the bone marrow and the blood. "Studies into the mechanisms behind reduced DKK3 expression have revealed histone modification in cancers such as renal cell carcinoma, and hypermethylation of the DKK3 promoter in a vast number of human cancers including lung, bladder, breast, and leukemia." (PMID 23226679, 2012). "The use of demethylating agents to re-express DKK3 in cancers where promoter hypermethylation leads to gene silencing have been shown in studies using cell lines of several cancers including gastric, prostate, lung, and leukemia." (PMID 23226679, 2012). "Dkk-3 could function in a similar way, confirming that epigenetic inactivation of genes involved in senescence regulation plays a major role in the pathogenesis of leukaemia." (PMID 15226763, 2004).
malignant glioma (5 papers, 2016 to 2024). A grade III or grade IV glioma arising from the central nervous system. "The adenovirus REIC vector with the super gene expression system (Ad-SGE-REIC) was developed to overexpress REIC/Dkk-3, and it demonstrated in vitro and in vivo anti-tumor effects on malignant glioma." (PMID 36006934, 2022).
Atrophy (4 papers, 2018 to 2025). Any weakening or degeneration, especially through lack of use. "Notably, our findings demonstrated that the depletion of ZBED6 attenuated muscle atrophy by downregulating the expression of Dkk3, a key regulator of muscular atrophy, by directly binding to its promoter region." (PMID 40464206, 2025).
diabetes (4 papers, 2022 to 2025). "We found that Wnt pathway–related genes are downregulated with insulin‐deficient diabetes, whereas systemic myostatin inhibition with REGN647 resulted in lower Dkk3 gene expression." (PMID 38025035, 2023). "In the case of albuminuria, both donor age (p < 0.001), donor diabetes (p = 0.03) and the DKK3 value (p < 0.001) were statistically significant." (PMID 35646976, 2022). "Although the direct relationship between DKK3 and diabetes is not well-studied, the protein’s involvement in CKD and CVD, both of which are common diabetes complications, suggests that DKK3 could be an indirect marker for managing diabetes-related complications." (PMID 40568561, 2025).
experimental autoimmune encephalomyelitis (4 papers, 2015 to 2023). An autoimmune demyelinating disease of the central nervous system that is produced experimentally in animals by the injection of homogenized brain or spinal cord in Freund's adjuvant. "Onset and severity in the acute phase of experimental autoimmune encephalomyelitis in Dkk3-deficient mice was comparable to WT controls." (PMID 25759692, 2015). "In an autoimmune context, DKK3 produced locally by stromal cells in the skin was found to reduce self-antigen–induced experimental autoimmune encephalomyelitis symptoms in a CD4+ T cell–dependent fashion." (PMID 37847565, 2023). "A previous study showed that genetic deletion or antibody-mediated neutralization of DKK3 exacerbated experimental autoimmune encephalomyelitis (EAE) with increased IFN-γ production." (PMID 36106640, 2022). "Moreover, genetic deletion or antibody-mediated neutralization of Dkk3 led to an exacerbated experimental autoimmune encephalomyelitis (EAE)." (PMID 25759692, 2015).
gallbladder cancer (4 papers, 2019 to 2022). "Here we demonstrate possible association of reduced expression of DKK3 with high-grade gallbladder carcinoma." (PMID 31737564, 2019). "Our proteomics and phosphoproteomics data analysis revealed that alteration was majorly seen at phosphorylation level upon DKK3 overexpression in gallbladder cancer cells." (PMID 33670899, 2021). "Our study highlights downstream effect of DKK3 overexpression at global proteomic and phosphoproteomic levels in gallbladder cancer cell lines, however the deeper validation of these integrated signaling molecules would provide a more explicit visualization." (PMID 33670899, 2021). "To identify downstream regulators of DKK3 signaling pathway, we transiently overexpressed DKK3 in 3 gallbladder cancer cell lines TGBC24TKB, OCUG-1, and G-415 cell lines." (PMID 33670899, 2021). "DKK3 is a secreted protein, which belongs to a family of Wnt antagonists and acts as a potential tumor suppressor in gallbladder cancer." (PMID 33670899, 2021). "Our previous study has identified DKK3 as a potential tumor suppressor in gallbladder cancer, which affects cell invasion, proliferation, and colony forming abilities in GBC cell lines." (PMID 33670899, 2021). "We observed that DKK3 expression was negligible in invasive gallbladder cancer cell lines OCUG-1, NOZ, and G415." (PMID 31737564, 2019). "In coherence with retrospective observation from different cancers, we further confirm functionally repressed DKK3 in gallbladder carcinoma cells." (PMID 31737564, 2019). "Our previous study, identified DKK3 as potential tumor suppressor in gallbladder cancer." (PMID 33670899, 2021).
liver cancer (4 papers, 2022 to 2024). An epithelial or non-epithelial malignant neoplasm that arises from the liver. "The intensified Wnt/β-catenin signaling seen in the aged gastric organoids resulting from decreased Dkk3 expression led to induction of the transcription factor Tbx3, which is a Wnt/β-catenin signaling target gene involved in the survival of liver cancer cells." (PMID 36923312, 2022). "Thus, our result suggested that secreted DKK3 may effectively penetrate the tumor mass, resulting in fractional killing, which is consistent with the results of previous reports showing that an adenovirus carrying DKK3 induced apoptosis in bladder, prostate, biliary, and liver cancers." (PMID 35205672, 2022).
malignant mesothelioma (4 papers, 2014 to 2022). A malignant neoplasm of the pleura or peritoneum, arising from mesothelial cells. "To verify that clinical samples can be measured using our measurement system, we quantified methylated and unmethylated DKK3 copies in ccfDNA from 21 patients with malignant mesothelioma." (PMID 35562749, 2022). "Finally, we quantified methylated and unmethylated DKK3 copies in ccfDNA from 21 patients with malignant mesothelioma." (PMID 35562749, 2022). "Overexpression of REIC/Dkk-3 in malignant mesothelioma (MM) down-regulates Id1 expression via activation of ATF3 and Smad, resulting in enhanced JNK phosphorylation and REIC/Dkk-3-induced apoptosis." (PMID 28122577, 2017). "Our previous studies demonstrated that the intratumoral injection of an adenovirus vector carrying the human REIC/Dkk-3 gene (Ad-REIC) suppresses tumor growth in mouse models of prostate, breast and testicular cancer and malignant mesothelioma." (PMID 24527065, 2014).
metastatic disease (4 papers, 2010 to 2021). "These facts strongly suggest that REIC/Dkk-3 shows an indirect anti-tumor effect through the anti-tumor immune system that is an important factor in the treatment of metastatic disease." (PMID 24498395, 2014). "The authors demonstrated significant over-expression of DKK3 in esophageal adenocarcinoma, promoting increased proliferation, invasion, and chemoresistance, and they suggested it may play an important role in tumor growth and metastatic disease." (PMID 34503162, 2021). "Moreover, injection of a DKK3-expressing adenovirus into the tumors of a patient with incurable PCa reduced metastatic tumor growth, and an early stage clinical trial found that intra-prostatic injection of DKK3 adenovirus significantly improved survival of patients with high-risk localized PCa." (PMID 29843383, 2018). "Another interesting candidate gene for the bypass of the AR pathway was the DKK3 tumor suppressor, which was down-regulated in PC346DCC and multiple databases of primary and metastatic tumors." (PMID 20976069, 2010).
acute lymphoblastic leukemia (3 papers, 2009 to 2019). Leukemia with an acute onset, characterized by the presence of lymphoblasts in the bone marrow and the peripheral blood. "However, whether other mechanisms lead to DKK3 inactivation and the subsequent effects of these inactivations on cell proliferation and the Wnt signaling pathway in adult B acute lymphoblastic leukemia (B-ALL) remain unclear." (PMID 28969056, 2017).
Arthritis (3 papers, 2022 to 2026). Inflammation of a joint. "Cluster 5 contains the bulk of the mouse S2d(Dkk3/Lrrc15+) SLSFs and M5 is linked to human cells in both clusters 5 and 6, suggesting that both human clusters (H5 and 6) likely acquire the “intermediate” arthritis-specific profile previously identified in hTNFtg SF states." (PMID 35879783, 2022). "The development of arthritis leads to shrinkage of homeostatic SFs and favors the emergence of SF profiles marked by Dkk3 and Lrrc15 expression, functioning towards enhanced inflammatory responses and matrix catabolic processes." (PMID 35879783, 2022). "Concomitantly with the shrinkage of the stably present SLSFs, we observed the emergence of arthritis-specific Thy1+ SF subpopulations (Dkk3/Lrrc15+ and Birc5/Aqp1+), accompanied by expansion of Prg4high/Thy1-LSFs." (PMID 35879783, 2022). "Additionally, many of the other proteins have been indicated in arthritis or pain conditions such as VEGFR3, FGR, TNFRSF6B, FGF19, DKK3 and proteins belonging to CCL, MMP and CXCL families." (PMID 41170664, 2025). "We then used imaging mass cytometry (IMC) to detect CD2+MHC-II+CCR2+ myeloid precursors and CD200+ (DKK3+FAP+CD45−CD31−) fibroblasts in the synovial tissues of individuals with early PsA who had just developed arthritis and individuals with psoriasis without arthritis." (PMID 41482544, 2026).
breast tumour (3 papers, 2013 to 2021). "DKK3 also induced changes of cell morphology, and inhibited breast tumour cell migration through reversing epithelial-mesenchymal transition (EMT) and down-regulating stem cell markers." (PMID 23890219, 2013). "Ectopic expression of DKK3 suppressed cell colony formation through inducing G0/G1 cell cycle arrest and apoptosis of breast tumour cells." (PMID 23890219, 2013). "Two genes, ITIH5 and DKK3, met our defined criteria, and were highly specifically unmethylated in sera from healthy women and those affected with benign disease, as well as sera from non-breast tumors." (PMID 23320751, 2013). "DKK3 was methylated in 78% (75/96) of breast tumours and 12.5% of (2/16) normal breast tissues, but not in surgical margins examined (P < 0.05)." (PMID 23890219, 2013).
carotid atherosclerosis (3 papers, 2017 to 2021). A thickening and loss of elasticity of the walls of carotid arteries that occur with formation of atherosclerotic plaques. "In a prospective population-based study, the expression of plasma DKK3 was inversely related to the 5-year progression of carotid atherosclerosis." (PMID 34631806, 2021).
dialysis (3 papers, 2021 to 2024). "It is conceivable that reduced urinary DKK3 levels reflect diminished renal stress responses also in peritoneal dialysis, however, mechanistic data remain to be obtained." (PMID 39179976, 2024). "DKK3 concentrations in serum, urine and peritoneal dialysate were assessed in a cohort of prevalent peritoneal dialysis outpatients." (PMID 39179976, 2024). "It would be intriguing to speculate that DKK3 may indeed reflect the tendency towards increased fibrosis, one of the mechanisms leading to kidney failure in ADPKD that is not well-reflected by currently available biomarkers." (PMID 38186869, 2024).
esophageal cancer (3 papers, 2021 to 2023). A primary or metastatic malignant neoplasm involving the esophagus. "DKK3 was previously shown to bind to Cytoskeleton-Associated Protein 4 (CKAP4) on esophageal cancer cells, and DKK3 and CKAP4 were found to be required for the phosphorylation of the Akt serine/threonine kinase in HNSCC cell lines." (PMID 38022675, 2023). "High-level expression of DKK-3 is associated with chemoresistance and tumor volume progression in HNSCC, pancreatic and esophageal cancer, and with poorer outcomes in HNSCC and esophageal cancer patients." (PMID 38201279, 2023). "Similarly, DKK3 was discovered to be downregulated in various types of malignant tissue, but there are also reports of DKK3 overexpression in hepatocellular and esophageal cancer." (PMID 34064046, 2021).
fibrosis (3 papers, 2023 to 2025). the formation of excess fibrous connective tissue in an organ or tissue in a reparative or reactive process. "Fibrosis-associated biomarkers such as Matrix Metalloproteinase-7 (MMP-7), Monocyte chemoattractant protein-1 (MCP-1), and Dickkopf-3 (DKK3) have been proposed as indicators of progressive CKD, particularly in high-risk patients." (PMID 40428218, 2025). "Cluster 10 (fibroblast-Wif1) showed increased expression of genes (Wif1, Dkk3, Sfrp1, Sfrp2) involved in negative regulation of Wnt signaling pathway, which has been considered to inhibit cardiac fibrosis." (PMID 36805782, 2023). "In addition, we investigated the expression of DKK3 in siNENs, as DKK3 has been reported to be involved in the development of renal and cardiac fibrosis, and its role in tumorigenesis has been investigated in various cancers." (PMID 35796776, 2023).
heart failure (3 papers, 2021 to 2024). Inability of the heart to pump blood at an adequate rate to meet tissue metabolic requirements. "This is somewhat reminiscent of cardiac DKK3 expression by the strained cardiac tissue in heart failure." (PMID 39179976, 2024). "These cardioprotective effects of Dkk3 are exerted via the inhibition of the Wnt non-canonical ASK1/JNK/p38 signaling pathways and has led to the proposal of Dkk3 as a therapeutic target for the treatment of heart failure." (PMID 35626694, 2022).
Hepatic steatosis (3 papers, 2023 to 2025). Steatosis is a term used to denote lipid accumulation within hepatocytes. "Finally, hepatic expression of DKK3 is linked to obesity and fatty liver disease, and genetic polymorphisms in this gene are associated with increased back fat thickness in pigs." (PMID 40662169, 2025). "Similarly, DKK3 was described to function as a negative regulator of insulin resistance and hepatic steatosis." (PMID 38137817, 2023). "Interestingly, some genes that have been described to suppress the high body fat phenotype, hepatic steatosis, and potentially also myosteatosis are strongly downregulated in tumors because they are putative tumor-suppressor genes, such as SFRP1, SFRP5, and DKK3." (PMID 38137817, 2023).
hepatoblastoma (3 papers, 2016 to 2019). Hepatoblastoma (HB) is a malignant hepatic tumor and is the most common pediatric liver cancer. "Together, these in vitro and in vivo data suggest that DKK3 promotes proliferation, migration, and survival in hepatoblastoma cells." (PMID 27788486, 2016). "Thus, the GATA4/miR125b/DKK3 axis might serve as a novel therapeutic target in pediatric hepatoblastoma patients." (PMID 27788486, 2016). "DKK3 is part of the Wnt signaling pathway and is overexpressed in hepatoblastomas, regardless of tumor histology." (PMID 29228658, 2017).
Hypertension (3 papers, 2021 to 2025). The presence of chronic increased pressure in the systemic arterial system. "Collectively, these findings suggest that DKK3 deficiency contributes to hypertension only under certain conditions." (PMID 40948935, 2025). "Together, higher DKK3 levels are associated with increased presence of cardiovascular risk factors, particularly age, male sex, history of hypertension, CKD, CVD and higher cholesterol levels." (PMID 33883651, 2021). "After the adjustment for gender, age, hypertension, and smoking, increasing DKK3 level still showed an increasing trend in the odds ratio (OR = 1.003, 95% CI = 1.000 to 1.006, P = 0.085)." (PMID 40948935, 2025). "The logistic regression model for the development of CI-AKI, using the parameters of DKK3/creatinine, albumin/creatinine, eGFR and age and hypertension, provided an AUC of 0.75 (95% CI 0.71–0.79)." (PMID 33275197, 2021). "Regression analysis implementing DKK3/creatinine, eGFR, age and hypertension showed an AUC of 0.77 (95% CI 0.72–0.81)." (PMID 33275197, 2021). "Logistic regression including DKK3/creatinine, albumin/creatinine, eGFR, age and hypertension computed an AUC of 0.74 (95% CI 0.69–0.78)." (PMID 33275197, 2021).